HLA-DRB1 (major histocompatibility complex, class II, DR beta 1)
Diseases named in the same sentence as HLA-DRB1 in open-access papers (continued):
Sharing a sentence is not in itself a finding about the gene and the disease.
Achalasia (3 papers, 2018 to 2023). A disorder of esophageal motility characterized by the inability of the lower esophageal sphincter to relax during swallowing and by inadequate or lacking peristalsis in the lower half of the body of the esophagus. "We also found a significant increase in the frequency of the HLA-DRB1*0407 allele (pC = 0.01, OR = 1.85; 95% CI = 1.14–3.01) in the achalasia group." (PMID 30092016, 2018). "Here, we found a significant association between HLA-DQB1*05:03 and HLA-DRB1*14:54 alleles and achalasia, and strong LD results associated the entire HLA-DRB1*14:54-DQB1*0503 haplotype with this clinical condition." (PMID 30092016, 2018). "Concluding, the HLA class II alleles HLA-DRB1*14:54:01 and DQB1*05:03:01 and the extended haplotype are risk factors for achalasia in mixed-ancestry Mexican individuals." (PMID 30092016, 2018). "MHC class II genes (HLA-DRB1*15:54 and DQB1*05:03) and the conserved haplotype DRB1*14:54-DQB1*05:03 confer risk for the development of achalasia in mixed-ancestry Mexicans." (PMID 30092016, 2018). "Analysis of the HLA-DRB1/-DQB1 blocks revealed an association between Eurasian origin haplotypes and achalasia." (PMID 30092016, 2018). "We also found a significant correlation between the presence of HLA-DRB1*14:54-carrying haplotypes in patients with achalasia that use tobacco (p = 0.02) and patients with BMIs higher than 25 (p = 0.03)." (PMID 30092016, 2018). "In this study, we classified HLA class I (HLA-C/-B) and class II (HLA-DRB1/-DQB1) blocks according to their most probable ancestry (MPA) in both the achalasia group and the control group." (PMID 30092016, 2018). "Maximum likelihood analysis revealed that the HLA-DQB1 locus in patients with achalasia and the HLA-DRB1 locus in controls had marginal significant deviations from Hardy-Weinberg equilibrium (HWE) after Bonferroni correction (p <0.05)." (PMID 30092016, 2018). "Thirteen genes associated with risk alleles of achalasia exhibited differential expression in C1QC+ macrophages, including CUTA and HLA-DQB1, compared with 18 risk genes that overlapped with DEGs in TRM, including HLA-DRB1 and HLA-DPB1." (PMID 37542039, 2023). "Gene frequencies of HLA-DRB1 in achalasia patients and healthy controls." (PMID 30092016, 2018). "Interestingly, CEHs carrying the susceptibility alleles HLA-DRB1*14:54 and DQB1*05:03, presumably of Eurasian MPA origin, were detected in only achalasia patients and not in the controls." (PMID 30092016, 2018).
acute GVHD (3 papers, 2007 to 2022). "An analysis of NMDP in 2004 indicated that HLA-A allele level mismatching, HLA-B serological mismatching, and DRB1 mismatching are significant risk factors for severe acute GVHD and that disparity in HLA class I and/or HLA-DRB1 increases the incidence of mortality." (PMID 23082252, 2012). "HLA-B*51, HLA-B*52 and HLA-DRB1*15 had a significant decreasing impact on the incidence of grades II-IV acute GVHD." (PMID 37543907, 2022). "We determined that acute GVHD grade II-IV occurrence was remarkably increased in the presence of HLA-B*07 and HLA-DRB1*07." (PMID 37543907, 2022). "The probability of grades III–IV acute GVHD was 61% among haplotype-mismatched patients who differed in linkage from HLA-B to HLA-A and 62% among those who differed in linkage from HLA-B to HLA-DRB1." (PMID 17378697, 2007).
Chagas disease (3 papers, 2012 to 2025). A parasitic infection caused by Trypanosoma cruzi. "We analyzed 4-digit HLA-DRB1 alleles for association with Chagas disease clinical manifestations." (PMID 22448298, 2012). "Importantly, the intensity of this response correlates with clinical indicators of impaired ventricular function, providing compelling evidence as to the involvement of HLA-DRB1 alleles in the selection of pathogenic antigens, promotion, and amplification of cardiac pathology in Chagas disease." (PMID 40391216, 2025). "We found that specific HLA-DRB1 alleles (*0103, *0402, *1301, and *1302) that display the DERAA motif are linked to this severe clinical manifestation of Chagas disease." (PMID 40391216, 2025). "All those genes are involved in biological process associated to Chagas disease: nervous system (LHX6, POU6F2, MDGA1, DISC1, PCSK9), immune system (ZMIZ, HLA-DRB1), Wnt pathway (DISC1), ion transport (KCNK15, PCSK9), striated muscles (SMYD3) or ATP metabolic process (ATP5S)." (PMID 36248819, 2022).
Cirrhosis (3 papers, 2022 to 2024). A chronic disorder of the liver in which liver tissue becomes scarred and is partially replaced by regenerative nodules and fibrotic tissue resulting in loss of liver function. "Our findings indicated the considerable impact of HLA‐DRB1 alleles on the risks of cirrhosis, providing valuable insights into the correlation between genetic predisposition and cirrhosis in patients with PBC." (PMID 39099389, 2024). "On this basis, our study explored the role of depressive symptoms and HLA‐DRB1 alleles on the progression of cirrhosis in patients with PBC." (PMID 39099389, 2024). "Next, we explored the effects of HLA‐DRB1 alleles which were associated with depressive symptoms on cirrhosis in patients with PBC." (PMID 39099389, 2024). "In addition to the production of autoantibodies, HLA‐DRB1 alleles were also associated with cirrhosis in patient with PBC." (PMID 39099389, 2024). "Notably, by employing Lasso‐logistic regression for feature selection and CART analysis for visualization of risk variables, we established a reliable risk model for cirrhosis which took depressive symptoms and HLA‐DRB1 alleles into consideration." (PMID 39099389, 2024). "Moreover, HLA‐DRB1 alleles might also confer a risk or protective effect on cirrhosis in patients with PBC." (PMID 39099389, 2024). "In addition, we investigated the potential association between HLA‐DRB1 alleles and cirrhosis." (PMID 39099389, 2024). "Finally, our scRNAseq analysis shows the presence of DAMs in the liver of NAFLD patients, which share the same phenotype, including expression of TREM2, CD9, GPNMB, MHCII (HLA-DRB1), C1QA, and CLEC10A, as those found in the livers of patients with NASH and cirrhosis." (PMID 38280848, 2024).
cutaneous melanoma (3 papers, 2004 to 2022). A primary melanoma arising from atypical melanocytes in the skin. "HLA-DRB1*04 is significantly associated with cutaneous melanoma in white persons in Alabama and Australia." (PMID 15310399, 2004). "The rationale for using country of ancestry information and HLA-DRB1*04 to identify persons who have increased risk to develop cutaneous melanoma is discussed." (PMID 15310399, 2004). "In addition, HLA-DRB1*04 was reported positively associated with cutaneous melanoma in white patients who had a high index of Celtic ancestry." (PMID 15310399, 2004). "Because this finding was unexpected and differed from that of previous reports we then computed the frequencies of HLA-DRB1*04 in Alabama white cutaneous melanoma probands and in control subjects from two previous Alabama reports." (PMID 15310399, 2004). "White adults with cutaneous melanoma in central Alabama have a predominance of Irish, Scots, and "British Isles" ancestry and HLA-DRB1*04 that likely contributes to their high incidence of cutaneous melanoma." (PMID 15310399, 2004). "Observations from previous studies demonstrate that the frequency of positivity for the HLA-DRB1*04 phenotype is significantly greater in Alabama cutaneous melanoma probands than in control subjects." (PMID 15310399, 2004). "In this study, we found that HLA-DRB1 may be a new potential prognostic factor and therapeutic target of cutaneous melanoma and an indicator of tumor microenvironment remodeling according to a series of bioinformatics analyses." (PMID 36129956, 2022). "Further, previous reports from Alabama suggest that the subgroup of individuals who possess HLA-DRB1*04 are at increased risk for cutaneous melanoma, independent of eye color, hair color, amount of melanin in the skin, or ethnic origin." (PMID 15310399, 2004). "HLA-DRB1 phenotypes were available for 63 of the 90 present cutaneous melanoma probands." (PMID 15310399, 2004).
demyelinating disease (3 papers, 2021 to 2025). A broad group of disorders that affect the myelin sheaths that cover the neurons. "Our data suggest that HLA-DRB1 alleles associated with demyelinating diseases may also confer risk of CNS IDD outcomes in patients with CHIKV infection." (PMID 33815474, 2021). "For example, individuals with certain protective haplotypes (HLA-DRB1) may still develop MS, albeit with a milder, relapsing form of demyelinating disease." (PMID 40260361, 2025).
dermatomyositis (3 papers, 2020 to 2025). Dermatomyositis (DM) is a type of idiopathic inflammatory myopathy characterized by evocative skin lesions and symmetrical proximal muscle weakness. "Genetic factors play a significant role in the pathogenesis of dermatomyositis, alleles HLA-DRB1*03:01 and HLA-DQA1*05:01 are strongly associated with disease susceptibility." (PMID 41293157, 2025). "C4A deficiency is relevant in dermatomyositis, HLA-DRB1*03 is important in IBM and both C4A deficiency and HLA-DRB1*03 contribute interactively to risk of polymyositis." (PMID 36171069, 2023). "The strongest disease association with alleles of the human leukocyte antigen (HLA) 8.1 ancestral haplotype—HLA-DRB1*03:01 and HLA-B*08:01—occurs in the clinical diagnosis of polymyositis and dermatomyositis." (PMID 32810190, 2020).
diffuse large B-cell lymphoma (3 papers, 2016 to 2024). "Previous studies mention the predisposing role of HLA-B*08:01, HLA-DRB1*03:01, and HLA-DRB1*09 alleles in the case of diffuse large B-cell lymphoma." (PMID 38535155, 2024).
endometriosis (3 papers, 2018 to 2020). The growth of functional endometrial tissue in anatomic sites outside the uterine body. "A literature search identified similar reports from China, which showed an association between endometriosis and the HLA-B*46, HLA-DRB1*15, and HLA-DQA1*0401 alleles." (PMID 32184413, 2020). "In a recent study, PCR-restriction fragment length polymorphism analysis revealed that the HLA-DRB1*14:03 and HLA-DQB1*03:01 alleles are associated with endometriosis in Japanese women." (PMID 32184413, 2020). "However,it is worth to mention that other class of MHC genes located near HLA-G (HLA-DQ and HLA-DRB1) have already been published in the context of endometriosis." (PMID 29234882, 2018).
endothelial dysfunction (3 papers, 2012). In vascular diseases, endothelial dysfunction is a systemic pathological state of the endothelium (the inner lining of blood vessels) and can be broadly defined as an imbalance between vasodilating and vasoconstricting substances produced by (or acting on) the endothelium. "HLA-DRB1 SE alleles are related to chronic inflammation, endothelial dysfunction, premature death, and CVD itself." (PMID 23193471, 2012). "Moreover, among the several HLA-DRB1 alleles involved in RA susceptibility, HLA-DRB1*0404 is associated with an increased risk of endothelial dysfunction and CVD events in RA patients." (PMID 23024462, 2012). "Furthermore, HLA-DRB1 *04 SE alleles, in particular HLA-DRB1 *0404, were associated with endothelial dysfunction, manifested by an impaired FMD and presence of atherosclerotic plaques." (PMID 22927710, 2012).
epilepsy (3 papers, 2021 to 2025). A brain disorder characterized by episodes of abnormally increased neuronal discharge resulting in transient episodes of sensory or motor neurological dysfunction, or psychic dysfunction. "Among the 145 epilepsy patients treated with OXC, eight (88.89%) of nine patients with HLA-DRB1*04:06 developed MPE." (PMID 34122097, 2021).
Felty syndrome (3 papers, 2005 to 2025). Felty syndrome (FS), also known as ''super rheumatoid'' disease, is a severe form of rheumatoid arthritis (RA), characterized by a triad of RA, splenomegaly and neutropenia, resulting in susceptibility to bacterial infections. "In this large sample of patients with ExRA, Felty's syndrome was the only manifestation that was clearly associated with HLA-DRB1*0401." (PMID 16277691, 2005). "In this large sample of patients with severe ExRA, we found Felty's syndrome to be associated with HLA-DRB1*0401." (PMID 16277691, 2005). "Felty’s syndrome was suggested by older studies showing a frequent expression of HLA-DRB1 alleles, especially HLA-DRB1*04:01 and HLA-DRB1*04:04 (HLA = human leukocyte antigen)." (PMID 40255577, 2025). "Another similarity of Felty’s syndrome and T-LGL leukemia was suggested by older studies showing a frequent expression of HLA-DRB1 alleles, especially HLA-DRB1*04:01 and HLA-DRB1*04:04 (HLA = human leukocyte antigen)." (PMID 37920595, 2023). "The homozygous genotype HLA-DRB1*0401/0401 was significantly more frequent in patients with Felty's syndrome (genotype frequency 0.286; P = 0.002) and patients with pericarditis (genotype frequency 0.185; P = 0.043) than in non-ExRA controls (frequency 0.068)." (PMID 16277691, 2005). "HLA-DRB1 was expressed in 90% of cases with Felty’s syndrome." (PMID 40255577, 2025). "HLA-DRB1*0401 was significantly associated with Felty's syndrome (allele frequency 0.475; P = 0.003) but not with other individual manifestations when compared with non-extra-articular RA." (PMID 16277691, 2005).
gastritis (3 papers, 2013 to 2025). Inflammation of the stomach. "To test this hypothesis, we analyzed the frequency of HLA-DRB1 alleles in a cross-sectional study in a Turkish patient cohort with gastritis symptoms who had available blood samples and histopathological tissue slides." (PMID 38540398, 2024). "Consistent with that expectation, we observed opposing tendencies for gastritis patients carrying HLA-DRB1*03:01 versus HLA-DRB1*11:04 genotypes." (PMID 38540398, 2024). "Furthermore, in the gastric mucosa of the patients with H. pylori-infected gastritis, USP15, ZNF451, TGFB1, and CCNT were identified as participants in the TGF-β signaling pathway, while FYB, HLA-DRB1, ANKRD24, and TMEM35 were implicated in T lymphocyte differentiation and immune response processes." (PMID 41035878, 2025).
Goodpasture syndrome (3 papers, 2015 to 2023). "Goodpasture syndrome after alemtuzumab was shown to be associated with the susceptibility allele HLA-DRB1-15, which is also a strongly linked genetic risk factor for MS." (PMID 26204829, 2015).
hepatocellular carcinoma (3 papers, 2010 to 2021). A malignant tumor that arises from hepatocytes. "Subgroup analysis by ethnicity showed that HLA-DRB1*15 allele significantly increased the risk of hepatocellular carcinoma in Asians under the fixed effect model (OR = 2.88, 95% CI: 1.77-4.69, P < 0.001)." (PMID 21172035, 2010). "The odds ratios (ORs) of HLA-DRB1 allele distributions in patients with hepatocellular carcinoma were analyzed against healthy controls." (PMID 21172035, 2010). "Subgroup analysis by ethnicity showed that HLA-DRB1*12 allele significantly increased the risk of hepatocellular carcinoma in Asians (OR = 1.73, 95% CI: 1.17-2.57, P = 0.006)." (PMID 21172035, 2010). "HLA-DRB1 allele polymorphisms have been reported to be associated with hepatocellular carcinoma susceptibility, but the results of these previous studies have been inconsistent." (PMID 21172035, 2010). "Subgroup analysis by ethnicity showed that HLA-DRB1*07 allele significantly increased the risk of hepatocellular carcinoma in Asians under the fixed effect model (OR = 2.10, 95% CI: 1.06-4.14, P = 0.03)." (PMID 21172035, 2010). "Moreover, previous studies showed that the MHC genes share a common influence on HBV infection, liver cirrhosis, hepatocellular carcinoma as well as associate with different risk in these outcomes; i.e. HLA-DQ, STAT4, C2, HLA-DRB1 for liver cirrhosis and HCC, HLA-DQ for CHB." (PMID 33736632, 2021). "To test whether genetic variation in HLA-DRB1 gene, a key component of HLA system, can predict its predisposition to hepatocellular carcinoma (HCC), we thereby conducted an association study by genotyping 8 nonsynonymous polymorphisms in HLA-DRB1 gene among 257 HCC patients and 264 controls." (PMID 27821814, 2016).
HIV-1 infection (3 papers, 2014 to 2024). The type species of lentivirus and the etiologic agent of acquired immunodeficiency syndrome (AIDS). "In the context of HIV-1 infection, at least two earlier studies have alluded to sex-specific findings with HLA-A*74:01 and HLA-DRB1*11." (PMID 24969460, 2014).
Hodgkins lymphoma (3 papers, 2022 to 2024). A heterogeneous group of malignant lymphoid neoplasms of B-cell origin characterized histologically by the presence of Hodgkin and Reed-Sternberg (HRS) cells in the vast majority of cases. "Both MS and Hodgkin’s lymphoma have been associated with the HLA-DRB1*1501, DQA1*01:02, and DQB1*06:02 haplotypes." (PMID 35894054, 2022). "Therefore, MS, Hodgkin’s lymphoma, and late-onset MG have a common genetic predisposition: HLA-DRB1*1501, DQA1*01:02, and DQB1*06:02." (PMID 35894054, 2022).
Hypercalcemia (3 papers, 2022 to 2025). An abnormally increased calcium concentration in the blood. "Accordingly, it is judicious to advise patients with elevated s-ACE and HLA-DRB1*04 carriage to avoid excessive exposure to the sunlight as well as to monitor them for hypercalcemia especially during the light period of the year." (PMID 39939699, 2025). "HLA-DRB1*04 was more frequent in the group with severe hypercalcemia, compared to the mild group (67% vs. 32%, p < 0.01)." (PMID 39939699, 2025).
idiopathic thrombocytopenic purpura (3 papers, 2019 to 2022). "Although the association of HLA-DRB1*04:10 with thyroid dysfunction has never been reported, its association with Vogt–Koyanagi–Harada disease and idiopathic thrombocytopenic purpura is known." (PMID 31412073, 2019).
infectious mononucleosis (3 papers, 2014 to 2025). A condition characterized by an increase in mononuclear white blood cells and swollen lymph nodes, which is usually caused by infection with the Epstein-Barr virus. "Previous infectious mononucleosis (IM) was associated with increased odds ratio (OR) of MS in HLA-DRB1*1501 positive but not HLA-DRB1*1501 negative persons." (PMID 32202208, 2020). "Age, gender, HLA-DRB1*15:01, smoking and infectious mononucleosis were included as covariates." (PMID 25274070, 2014).
interstitial lung disease (3 papers, 2005 to 2025). A diverse group of lung diseases that affect the lung parenchyma. "Recent studies suggest that specific HLA-DRB1 variants may predict unfavorable disease progression, including an increased risk of radiographic damage and a higher incidence of interstitial lung disease and lymphoproliferative disorders." (PMID 39484788, 2025). "In the case of interstitial lung diseases, most associations have implicated the locus HLA-DRB1." (PMID 36359012, 2022).